DGKI (diacylglycerol kinase iota)
Description:
Diacylglycerol kinase that converts diacylglycerol/DAG into phosphatidic acid/phosphatidate/PA and regulates the respective levels of these two bioactive lipids. Thereby, acts as a central switch between the signaling pathways activated by these second messengers with different cellular targets and opposite effects in numerous biological processes (Probable). Has probably no preference for any of the diacylglycerols in terms of the acyl chain composition, especially for the acyl chain at the sn-2 position. By controlling the diacylglycerol/DAG-mediated activation of RASGRP3, negatively regulates the Rap1 signaling pathway. May play a role in presynaptic diacylglycerol/DAG signaling and control neurotransmitter release during metabotropic glutamate receptor-dependent long-term depression (By similarity).
Synonyms: DGK-iota
Tractability: Antibody: its Gene Ontology location is reachable by antibodies, with high confidence; UniProt places it where antibodies can reach, with medium confidence. PROTAC: ubiquitination databases record sites on it; its protein half-life has been measured.
Target class: Enzyme; Transferase
Gene: Protein-coding gene on chromosome 7 (137,381,037 to 137,847,092, reverse strand). Ensembl gene ENSG00000157680.
Subcellular location: Cell projection, axon; Cell projection, dendrite; Presynapse; Postsynapse; Postsynaptic density; Synaptic cell membrane; Cytoplasmic vesicle, secretory vesicle, synaptic vesicle membrane; Cytoplasm, cytosol; Nucleus
Pathways (Reactome):
Hemostasis: Effects of PIP2 hydrolysis
Gene Ontology:
Molecular function: ATP-dependent diacylglycerol kinase activity; protein binding; GTPase inhibitor activity; kinase activity; small GTPase binding
Biological process: lipid phosphorylation; diacylglycerol metabolic process; intracellular signal transduction; phosphatidic acid biosynthetic process; platelet activation; glycerolipid metabolic process; phospholipase C-activating G protein-coupled receptor signaling pathway; presynaptic modulation of chemical synaptic transmission; signal transduction
Cellular component: cytoplasm; dendritic spine; nucleus; protein-containing complex; synapse; glutamatergic synapse; plasma membrane; postsynapse; postsynaptic density; presynapse; synaptic membrane; axon; cytosol; dendrite; guanyl-nucleotide exchange factor complex; perinuclear region of cytoplasm; Schaffer collateral - CA1 synapse; synaptic vesicle membrane
Genetic constraint (gnomAD): Loss-of-function variants: 36 observed, 111.08 expected, observed/expected ratio (o/e) 0.32, 90% interval 0.25 to 0.43. The upper end of that interval is the gene's LOEUF score, 0.43, which puts it in group 1 of 6, group 1 being the genes least tolerant of losing a copy. Missense variants: 900 observed, 1,153.6 expected, observed/expected ratio (o/e) 0.78, 90% interval 0.74 to 0.82. Synonymous variants: 426 observed, 421.7 expected, observed/expected ratio (o/e) 1.01, 90% interval 0.93 to 1.09.
Homologues: Orthologues: chimpanzee DGKI (99% identical), macaque DGKI (99% identical), pig DGKI (97% identical), rat Dgki (96% identical), mouse Dgki (96% identical), dog DGKI (91% identical), rabbit DGKI (85% identical), guinea pig DGKI (83% identical), tropical clawed frog dgki (72% identical), zebrafish DGKI (53% identical), Drosophila melanogaster rdgA (40% identical), Caenorhabditis elegans dgk-5 (31% identical), and 2 more. Paralogues in human: DGKZ (55% identical), DGKH (23% identical), DGKD (22% identical), DGKK (19% identical), DGKB (19% identical), DGKG (19% identical), DGKA (19% identical), DGKQ (17% identical), DGKE (16% identical).
Diseases named in the same sentence as DGKI in open-access papers:
DGKI is named in the same sentence as 33 diseases in open-access papers, as found by Europe PMC text mining. Sharing a sentence is not in itself a finding about the gene and the disease. The quoted sentences say what the papers report.
glioblastoma (3 papers, 2016 to 2022). The most malignant astrocytic tumor (WHO grade IV). "DGKI has also been reported to be associated with a better prognosis in glioblastoma." (PMID 36059514, 2022). "Interestingly, DGKI was listed among genes mutated in melanoma as identified by next generation sequencing and also among hypermethylated gene list identified by whole-genome methylation analysis of glioblastoma." (PMID 27047543, 2016).
melanoma (3 papers, 2016 to 2023). A malignant, usually aggressive tumor composed of atypical, neoplastic melanocytes. "We next tested whether DGKi could improve tumor control of TRP1high and TRP1low T cells against B16 melanoma, which expresses higher levels of Trp1 antigen." (PMID 38000024, 2023). "Other alterations were found in genes reportedly altered in skin cancer, such as DGKI and SYK in melanoma or BCOR, PIKFYVE and NEDD4 in SCC." (PMID 28410231, 2017). "To determine whether DGKi enhances suboptimal TCR signaling in effector CD8 T cells, we used both B16 melanoma cells and the pancreatic cancer cell line 6694c2 transduced to express low amounts of Tyrp1 (C2VTrp1)." (PMID 38000024, 2023).
Obesity (3 papers, 2020 to 2025). Accumulation of substantial excess body fat. "Several of the high-scoring genes (score ≥ 11) are known to be implicated in obesity (such as DGKI [score: 22.8], MC4R [19.6], BDNF [19.6], MTOR [16.8], SH2B1 [14.8], GIPR [14.3], AKT3 [11.6], and LEPR [11.6])." (PMID 38754426, 2024). "We identify three genes (PHIP, DGKI, and ZMYM4) newly implicated in obesity, harboring very rare predicted deleterious alleles, with intermediate effects and penetrance between those identified through family or large-population scale efforts." (PMID 32492392, 2020). "We next built a prioritization score that weighs each of the eight methods based on whether or not they prioritized one or more of the six established obesity genes located in any of the 536 BMI-associated loci (i.e., LEPR, POMC, PCSK1, DGKI, SH2B1, and MC4R)." (PMID 38754426, 2024).
schizophrenia (3 papers, 2015 to 2024). A major psychotic disorder characterized by abnormalities in the perception or expression of reality. "Actually, DGKI has been reported to be related with schizophrenia at gene level test (gene-wide Pmin = 6.7×10−4)." (PMID 26193471, 2015). "It is worth noting that three of our potential candidate genes for depressive episodes have previously shown associations with either major depression at the gene-level (DCC) or mapped to schizophrenia loci (CR1L and DGKI) in large GWASs." (PMID 38570518, 2024). "For five loci shared between openness and schizophrenia (BRINP2, SDCCAG8, PSORS1C1, DGKI and AK093940), the effect directions were concordant." (PMID 28533504, 2017).
colon cancer (2 papers, 2016 to 2020). "Recently, studies showed that DGKI was overexpressed in a variety of cancers and was associated with poor prognosis in colon cancer." (PMID 32733904, 2020). "LOH and immunohistochemistry supported the role of DGKI, EPCAM, and OPCML in clinical colon cancer specimens." (PMID 27047543, 2016).
Hypertension (2 papers, 2019 to 2020). The presence of chronic increased pressure in the systemic arterial system. "DGKI, as with other diacylglycerol products play a role in the tonal contraction of vascular smooth muscle, which has a role in hypertension." (PMID 30941163, 2019). "In addition, Ohanian and Ohanian showed that DGKI plays a role in regulating the contraction of vascular smooth muscle which plays a role in hypertension." (PMID 32733904, 2020).
liver cancer (2 papers, 2016 to 2022). An epithelial or non-epithelial malignant neoplasm that arises from the liver. "The latest studies have reported that DGKI is overexpressed in colon, gastric and liver carcinomas and is linked to an unsatisfactory prognosis." (PMID 36059514, 2022).
thyroid (2 papers, 2021 to 2022). "The 11 selected thyroid-specific RNA transcripts (TPO, TG, GFRA2, IYD, PDE8B, WDR86, C16orf89, DGKI, DIO2, TSHR, and PAX8) were amplified from healthy volunteers and thyroid patients." (PMID 34512731, 2021).
acute myeloid leukemia (1 paper, 2026). Acute myeloid leukemia (AML) is a group of neoplasms arising from precursor cells committed to the myeloid cell-line differentiation. "Higher DGKH expression has been associated with a shorter survival in acute myeloid leukemia, suggesting a possible involvement also of this isoform in the pathology as well as DGKι‐coding gene (DGKI) in gastric cancer." (PMID 40859612, 2026).
autoimmune disease (1 paper, 2019). A disorder resulting from loss of function or tissue destruction of an organ or multiple organs, arising from humoral or cellular immune responses of the individual to their own tissue constituents. "The genes harboring these mutations, including DGKI, TNFRSF10A, GNGT1, CPAMD8, and BAFF, which are expressed in both eye and brain tissues and/or are related to autoimmune diseases, provide new avenues to evaluate the inherited causes of these devastating autoimmune conditions." (PMID 31161422, 2019).
autoimmune thyroid disease (1 paper, 2022). Inflammatory disease of the thyroid gland due to autoimmune responses leading to lymphocytic infiltration of the gland. "The enrichment plots of the GSEA showed that thyroid hormone production and its peripheral downstream signalling effects, thyroxine biosynthesis, and autoimmune thyroid disease were significantly enriched in RGS8, DGKI and OCA2." (PMID 36059514, 2022). "The GSEA showed that RGS8, DGKI and OCA2 were enriched in thyroid hormone production and its peripheral downstream signal transduction effects, thyroxine biosynthesis, and autoimmune thyroid diseases." (PMID 36059514, 2022).
Autoimmunity (1 paper, 2023). The occurrence of an immune reaction against the organism's own cells or tissues. "This distinction bodes well for use of DGKi therapeutically where autoimmunity remains a significant concern for patients receiving checkpoint blockade immunotherapy." (PMID 38000024, 2023).
colorectal cancer (1 paper, 2016). A primary or metastatic malignant neoplasm that affects the colon or rectum. "Our data suggest that DGKI is a novel potential tumor suppressor in colorectal cancers and its expression is downregulated subsequent to β-catenin activation too." (PMID 27047543, 2016).
dyslexia (1 paper, 2020). A learning disorder characterized by an impairment in processing written words. "Common variants in the DGKI gene region have been associated with dyslexia; the patient with the nonsense mutation (Q265X) was reported to have speech and language delay." (PMID 32492392, 2020).
gastric cancer (1 paper, 2020). A primary or metastatic malignant neoplasm involving the stomach. "Univariate analysis and multivariate analysis of the correlation of DGKI expression with overall survival among patients with gastric cancer." (PMID 32733904, 2020). "This study evaluated the prognostic value of DGKI in gastric cancer (GC) using data from The Cancer Genome Atlas (TCGA)." (PMID 32733904, 2020).
gastric tumors (1 paper, 2020). "Our study found that DGKI was overexpressed in gastric tumors and was associated with a poor prognosis for patients." (PMID 32733904, 2020). "The difference in expression of DGKI between gastric tumors and normal tissues was statistically significant (p <0.001), indicating that DGKI was overexpressed in gastric tumors." (PMID 32733904, 2020).
papillary thyroid carcinoma (1 paper, 2022). "Then, we detected the protein expression of RGS8, DGKI and OCA2 in five pairs of papillary thyroid carcinoma tissues and found that their expression levels were obviously lower than those of the paired normal thyroid tissues." (PMID 36059514, 2022).
psychosis (1 paper, 2024). "A subset of 38 GWAS genes was common to all psychiatric disorders considered here; this includes genes such as GRIN2A, DGKI and SHISA9, which were previously known to be involved in multiple psychosis." (PMID 38864245, 2024).
thyroid cancer (1 paper, 2022). "Nevertheless, the association between DGKI and thyroid cancer has not been reported." (PMID 36059514, 2022). "To further investigate the significance and mechanism of RGS8, DGKI and OCA2 in thyroid cancer, we summarized the relationship between RGS8, DGKI and OCA2 expression and clinical features in the TCGA database of THCA patients." (PMID 36059514, 2022). "To investigate the role of RGS8, DGKI and OCA2 expression, we explored the relationship between RGS8, DGKI, and OCA2 expression and clinical features in thyroid cancer patients, and the expression data were obtained from TCGA." (PMID 36059514, 2022). "Our results revealed that the expression of RGS8, DGKI, and OCA2 in thyroid carcinoma was negatively correlated with multiple types of immune cell infiltration, including dendritic cells (DCs and aDCs), macrophages and neutrophils." (PMID 36059514, 2022). "In addition, RGS8, DGKI, and OCA2 were expressed at low levels in thyroid cancer in our sequencing results, GSE33630 and GSE29265." (PMID 36059514, 2022).
tumor (7 papers, 2016 to 2025). "Addition of DGKi markedly increased cytotoxicity of C2VTrp1 and 6694c2 parental tumor cells, indicating that DGKi enhances cytotoxicity of effector CD8 T cells in conditions where antigen is limited." (PMID 38000024, 2023). "6694c2 tumor growth was equivalent among all groups, indicating that endogenous T cell responses to 6694c2 cells are insufficient and that DGKi/αPD-1 enhances antigen-specific immunity by transferred TRP1 T cells." (PMID 38000024, 2023). "TRP1 T cells combined with DGKi or DGKi/αPD-1 treatment further delayed tumor growth and improved median survival." (PMID 38000024, 2023). "Upregulated genes included cartilage-associated genes (COMP, MATN3, and COL11A2), collagen- and extracellular matrix-associated genes (COL9A2, SFRP2, and SERPINE2), and tumor metastasis- and progression-associated genes (SLC38A3, FST, ITGA11, and DGKI)." (PMID 36192442, 2022). "By quantifying ssGSEA in the THCA tumor environment, we applied the Spearman correlation to prove the correlation between the level of immune cell infiltration and the expression of RGS8, DGKI and OCA2." (PMID 36059514, 2022). "Although OT-I T cells did not kill parental B16 tumor cells, we observed a small enhancement in cytotoxicity with DGKi." (PMID 38000024, 2023). "Similarly, by analysing RGS8, DGKI, and OCA2 expression in the TCGA database, we found that their expression in 58 THCA tumor samples was lower than that in 58 paired normal samples." (PMID 36059514, 2022). "However, recent studies showed that different BRAF fusions, such as GTF2I-BRAF, DGKI-BRAF, and TMEM106B-BRAF, activated the MAPK pathway, thereby regulating tumor growth in multiple cancers." (PMID 30111351, 2018). "Moreover, DGKi had a more profound effect on proliferation of lower-affinity TCR clones, demonstrating the potential impact of DGKi in overcoming a threshold required for activation of low-affinity tumor-specific T cells." (PMID 38000024, 2023). "Then, we used qRT–PCR and a Western blot analysis to detect the expression of RGS8, DGKI and OCA2 in tumor tissues and corresponding noncancer tissues from THCA patients." (PMID 36059514, 2022).
cancer (4 papers, 2018 to 2022). A tumor composed of atypical neoplastic, often pleomorphic cells that invade other tissues. "DGKI can expressed in the cytoplasmic matrix of human platelets; additionally, DGKI was recently found to be overexpressed in a variety of cancers, including GC." (PMID 35836573, 2022). "Pathways related to ECM receptor interactions, focal adhesion, calcium signaling, TGF-beta signaling, MAPK signaling, Hedgehog signaling, cell adhesion molecules (CAMs), adherens junctions, and cancer were differentially enriched with the DGKI high expression phenotype." (PMID 32733904, 2020). "GSEA found that pathways related to ECM receptor interactions, focal adhesion, calcium signaling, TGF-beta signaling, MAPK signaling, Hedgehog signaling, cell adhesion molecules (CAMs), adherens junctions, and cancer were differentially enriched with the DGKI high expression phenotype." (PMID 32733904, 2020). "First, using TISIDB, we analysed the relationship between the expression levels of RGS8, DGKI and OCA2 and the level of immune cell infiltration in different cancers." (PMID 36059514, 2022). "We first evaluated RGS8, DGKI, and OCA2 expression across cancers." (PMID 36059514, 2022).
retinopathy (1 paper, 2020). "Previous studies showed that DGKI was expressed in the retina and brain, suggesting that it may play an important role in retinopathy." (PMID 32733904, 2020).
DGKI also shares sentences with these, for which no sentence is quoted: hereditary colorectal cancers (1 paper); Insulin resistance (1); lung carcinoma (1); lymphocytic thyroiditis (1); Lynch syndrome (1); major depression (1); neurodegenerative disease (1); pancreatic cancer (1); pancreatic tumors (1); psychiatric disorder (1); skin cancer (1).